BRCC3 (BRCA1/BRCA2-containing complex subunit 3)
Description:
Metalloprotease that specifically cleaves 'Lys-63'-linked polyubiquitin chains. Does not have activity toward 'Lys-48'-linked polyubiquitin chains. Component of the BRCA1-A complex, a complex that specifically recognizes 'Lys-63'-linked ubiquitinated histones H2A and H2AX at DNA lesions sites, leading to target the BRCA1-BARD1 heterodimer to sites of DNA damage at double-strand breaks (DSBs). In the BRCA1-A complex, it specifically removes 'Lys-63'-linked ubiquitin on histones H2A and H2AX, antagonizing the RNF8-dependent ubiquitination at double-strand breaks (DSBs). Catalytic subunit of the BRISC complex, a multiprotein complex that specifically cleaves 'Lys-63'-linked ubiquitin in various substrates. Mediates the specific 'Lys-63'-specific deubiquitination associated with the COP9 signalosome complex (CSN), via the interaction of the BRISC complex with the CSN complex. The BRISC complex is required for normal mitotic spindle assembly and microtubule attachment to kinetochores via its role in deubiquitinating NUMA1. Plays a role in interferon signaling via its role in the deubiquitination of the interferon receptor IFNAR1; deubiquitination increases IFNAR1 activity by enhancing its stability and cell surface expression. Acts as a regulator of the NLRP3 inflammasome by mediating deubiquitination of NLRP3, leading to NLRP3 inflammasome assembly (By similarity). Down-regulates the response to bacterial lipopolysaccharide (LPS) via its role in IFNAR1 deubiquitination. Deubiquitinates HDAC1 and PWWP2B leading to their stabilization (By similarity).
Synonyms: BRCC36; C6.1A; CXorf53
Tractability: Small molecule: a structure with a bound ligand is known. PROTAC: ubiquitination databases record sites on it; its protein half-life has been measured.
Target class: Enzyme; Hydrolase
Gene: Protein-coding gene on chromosome X (155,071,420 to 155,123,077, forward strand). Ensembl gene ENSG00000185515.
Subcellular location: Nucleus; Cytoplasm; Cytoplasm, cytoskeleton, spindle pole
Subcellular location (Human Protein Atlas): Nucleoplasm
Pathways (Reactome):
DNA Repair: Nonhomologous End-Joining (NHEJ); Processing of DNA double-strand break ends; Recruitment and ATM-mediated phosphorylation of repair and signaling proteins at DNA double strand breaks
Cell Cycle: G2/M DNA damage checkpoint
Metabolism of proteins: Metalloprotease DUBs
Gene Ontology:
Molecular function: enzyme regulator activity; K63-linked deubiquitinase activity; metal-dependent deubiquitinase activity; metallopeptidase activity; polyubiquitin modification-dependent protein binding; protein binding; cysteine-type deubiquitinase activity; peptidase activity
Biological process: cellular response to ionizing radiation; DNA repair-dependent chromatin remodeling; double-strand break repair; mitotic G2 DNA damage checkpoint signaling; positive regulation of DNA repair; positive regulation of NLRP3 inflammasome complex assembly; protein K63-linked deubiquitination; response to ionizing radiation; response to X-ray; mitotic G2/M transition checkpoint; protein deubiquitination; regulation of DNA damage checkpoint; regulation of DNA repair; response to vitamin B6; DNA repair
Cellular component: BRCA1-A complex; BRISC complex; cytoplasm; nuclear ubiquitin ligase complex; nucleoplasm; nucleus; ubiquitin ligase complex; cytosol; spindle pole
Homologues: Orthologues: macaque BRCC3 (99% identical), chimpanzee BRCC3 (99% identical), rabbit BRCC3 (99% identical), dog FUNDC2 (99% identical), guinea pig BRCC3 (98% identical), pig BRCC3 (98% identical), mouse Brcc3 (97% identical), rat Brcc3dc (86% identical), mouse Brcc3dc (86% identical), zebrafish brcc3 (80% identical), tropical clawed frog brcc3 (77% identical). Paralogues in human: PSMD14 (24% identical), COPS5 (22% identical), EIF3H (19% identical).
Diseases named in the same sentence as BRCC3 in open-access papers:
BRCC3 is named in the same sentence as 59 diseases in open-access papers, as found by Europe PMC text mining. Sharing a sentence is not in itself a finding about the gene and the disease. The quoted sentences say what the papers report.
breast cancer (9 papers, 2008 to 2025). A primary or metastatic malignant neoplasm involving the breast. "The protein BRCC3 is a complex component containing breast cancer type 1 susceptibility protein and breast cancer type 2 susceptibility protein." (PMID 39968094, 2025). "Downregulation of BRCC3 has been associated with increased apoptosis in breast cancer cells following ionizing radiation and enhanced sensitivity towards temozolomide in human glioma cells." (PMID 31576005, 2020). "Moreover, mRNA expression profiling of BRCC3 has been reported in human breast cancer cells, and exogenous BRCC3 expression is associated with delayed death and increased breast cancer cell proliferation." (PMID 38449391, 2024). "Abnormal expression of BRCC3 has been observed in several breast cancer cell lines and invasive ductal carcinomas." (PMID 25337721, 2014). "BRCC3 depletion has been reported to enhance the cytotoxic effect of ionizing radiation on breast cancer cells." (PMID 25337721, 2014). "Given the fact that BRCC3 (BRCC36) is essential for the protection of breast cancer cells from ionizing radiation-induced DNA damage, a high level of BRCC3 could protect U251 and A172 cells from TMZ-induced cytotoxicity." (PMID 25337721, 2014). "The study has demonstrated that BRCC3 depletion prevents the formation of BRCA1 nuclear foci, and subsequently impairs the DNA repair pathway in response to DNA damage by ionizing radiation in breast cancer cells, suggesting that BRCC3 is referred as a potential therapeutic target for breast cancer." (PMID 25337721, 2014).
Moyamoya disease (5 papers, 2015 to 2025). Moyamoya disease (MMD) is a rare intracranial arteriopathy involving progressive stenosis of the cerebral vasculature located at the base of the brain causing transient ischemic attacks or strokes. "Case: We report the case of an adolescent male presenting with progressive and symptomatic moyamoya angiopathy and severe dilated cardiomyopathy caused by a hemizygous deletion of BRCC3/MTCP1." (PMID 33868155, 2021). "Loss-of-function mutations in F8 or in BRCC3 cause hemophilia A or moyamoya angiopathy, respectively." (PMID 33193636, 2020). "Further experiments in this study using Zebrafish models demonstrated that deletion of BRCC3 but not CMC4 results in defective angiogenesis, further confirming the role of BRCC3 in moyamoya disease." (PMID 33193636, 2020). "Recently, an ~150 kb deletion of Xq28 encompassing part of F8, FUNDC2, CMC4, MTCP1, and BRCC3 was reported in a child with severe hemophilia A, Moyamoya disease, and distinctive facial features." (PMID 25927380, 2015). "Deletions including FUNDC2, CMC4, MTCP1, and BRCC3 were reported in individuals with syndromic Moyamoya disease, characterized by angiopathy, short stature, and distinctive facial features." (PMID 25927380, 2015). "Additionally, inhibition of BRCC3 in zebrafish resulted in defective angiogenesis, suggesting a pathophysiological role of BRCC3 in moyamoya angiopathy." (PMID 39552268, 2025). "Furthermore, BRCC3 gene is also connected to MOYAMOYA disease which also has similar symptoms including short stature, hypergonadotropic hypogonadism, facial dysmorphism, and in some cases decreased testicular volume and azoospermia." (PMID 30093884, 2018). "The critical region of overlap for syndromic moyamoya disease among these three families encompasses exon 1 of CMC4 and MTCP1 and the first three exons of BRCC3." (PMID 33193636, 2020).
atherosclerosis (4 papers, 2024 to 2025). A disease characterized by the build-up of fatty material and calcium deposition in the arterial wall resulting in partial or complete occlusion of the arterial lumen. "In an atherosclerosis model, pharmacologic inhibition of BRCC3 or genetic deletion of the BRCC3 cofactor ABRO1 in immune cells reduced lesion area, inflammasome activation markers, and NETosis." (PMID 38705278, 2024). "Consequently, aberrant BRCC3 activation amplifies pro-inflammatory signaling, exacerbating vascular inflammation and atherosclerosis." (PMID 40376148, 2025). "Targeting BRCC3 represents a promising strategy to mitigate CH-induced atherosclerosis." (PMID 40376148, 2025). "Both ex vivo and in vitro studies indicated that hcmv-miR-US25-1 expression may accelerate atherosclerosis development and progression, likely due to the downregulation of BRCC3, a gene involved in DNA damage repair." (PMID 40565134, 2025). "Our findings indicate that the progression of early atherosclerosis and NETosis is promoted by a distinct pathway involving ER cholesterol accumulation, CaMKII/JNK activation, and BRCC3-mediated deubiquitylation of NLRP3." (PMID 38522750, 2024).
bladder cancer (4 papers, 2021 to 2025). "Recent studies have shed light on the association between BRCC3 and the activation of NF-κB signaling in bladder cancer." (PMID 38656882, 2024). "These intriguing findings shed light on the notion that BRCC3 is susceptible to ubiquitin-mediated degradation in bladder cancer cells." (PMID 38656882, 2024). "A study indicated that the expression of BRCC3 was increased in bladder cancer, which was associated with a poor prognosis." (PMID 37564930, 2023). "In summary, we found that BRCC3 is overexpressed and associated with a poor prognosis in bladder cancer." (PMID 34604222, 2021). "Next, we determined the function ofBRCC3 in the progression of bladder cancer using BRCC3 over-expressed and BRCC3 deficient cells in vitro." (PMID 34604222, 2021). "To reveal the way how BRCC3 promotes carcinogenesis, we analyzed BRCC3-deficient bladder cancer cell lines by RNA-Seq, and the data showed that the NF-κB inflammatory pathway was notably downregulated when BRCC3 was knockout." (PMID 34604222, 2021). "However, the role of BRCC3-associated NF-κB signaling activation in bladder cancer remains to be characterized." (PMID 34604222, 2021). "In conclusion, our study found a new significant mechanism that USP15 regulates the expression of NF-κB through BRCC3, resulting in increased proliferation of bladder cancer cells." (PMID 38656882, 2024). "It is worth noting that scientific investigations have established the up-regulation of BRCC3 protein as a catalyst for the hyperactivation of the NF-κB pathway, thereby driving bladder cancer progression." (PMID 38656882, 2024). "USP15 induced bladder cancer progression through reducing the degradation of BRCC3, thereby regulating the classical NF-κB signaling pathway." (PMID 38656882, 2024). "Previous studies have indicated that elevated levels of BRCC3 protein can lead to the hyperactivation of the NF-κB pathway in bladder cancer." (PMID 38656882, 2024). "In summary, our study demonstrates that USP15 can activate the NF-κB signaling pathway through BRCC3, thus enhancing the proliferation, migration, and invasiveness of bladder cancer cells." (PMID 38656882, 2024). "The results revealed that excessive expression of BRCC3 promoted the growth, invasion, and migration of bladder cancer cells and also counteracted the reduced proliferation and invasion caused by the inhibition of USP15 expression." (PMID 38656882, 2024). "Evidently, USP15 promotes the development of bladder cancer by stabilizing BRCC3, thereby activating the NF-κB signaling pathway." (PMID 38656882, 2024). "To confirm the results above, we performed an IHC analysis of BRCC3 using tissue microarrays, which contained 188 bladder cancer tissue samples, 12 corresponding adjacent tissue samples and 16 normal bladder tissue samples." (PMID 34604222, 2021). "Our study provides novel insight into the function of BRCC3 in the TRAF2-activating NF-κB signaling cascade in bladder cancer." (PMID 34604222, 2021). "Western blotting and IHC of tissue microarray were used to confirm the abnormal expression of BRCC3 in bladder cancer." (PMID 34604222, 2021). "And upregulated BRCC3 expression was negatively related to the diseases-free survival in patients with bladder cancer." (PMID 34604222, 2021). "To analyze the level of BRCC3 in bladder cancer, we first searched the Oncomine and GEPIA databases." (PMID 34604222, 2021). "The protein level of BRCC3 in bladder cancer in The Cancer Genome Atlas (TCGA) datasets showed that BRCC3 expression is aberrantly upregulated in bladder cancer patients." (PMID 34604222, 2021). "Although BRCC3 has emerged as an oncogene in various tumors, the role of BRCC3 in bladder cancer is still obscure." (PMID 34604222, 2021). "The mRNA levels of BRCC3 in bladder cancer tissue specimens were obviously upregulated, compared with those in normal bladder tissue samples." (PMID 34604222, 2021).
bladder cancer (continued). "Our findings showed BRCC3 plays a crucial role in facilitating the development and progression of bladder cancer." (PMID 34604222, 2021). "Growth curve, colony formation, soft agar assay and Xenograft model were performed to identify the role of BRCC3 over-expression or knock-out in bladder cancer." (PMID 34604222, 2021). "By in vitro and in vivo assays, we found genetic BRCC3 ablation markedly blocks proliferation, viability and migration of bladder cancer cells." (PMID 34604222, 2021). "To validate our hypothesis, we performed Western blotting to measure the amount of BRCC3 protein in bladder cancer cells with low USP15 expression." (PMID 38656882, 2024). "Thus, our results compellingly suggest that by modulating the ubiquitination of BRCC3, USP15 contributes to enhancing the stability of BRCC3 in bladder cancer cells." (PMID 38656882, 2024). "Taken together, these results implied BRCC3 was upregulated aberrantly in bladder cancer." (PMID 34604222, 2021). "We demonstrated that BRCC3 facilitates tumorigenesis via TRAF2 in bladder cancer." (PMID 34604222, 2021). "In this study, we reported BRCC3 as a novel oncogene in bladder cancer." (PMID 34604222, 2021). "To investigate whether USP15 can affect the growth, migration, and invasiveness of bladder cancer by regulating BRCC3, we generated bladder cancer cell models with different expression levels of USP15 and BRCC3 and evaluated their proliferative, migratory, and invasive capabilities." (PMID 38656882, 2024). "Moreover, we investigated the BRCC3 mRNA and protein levels in bladder cancer-derived cell lines and the immortalized normal uroepithelial cell line SV-HUC1, and found that 6 out of 8 cancer cell lines showed BRCC3 expression upregulation, compared with SV-HUC1." (PMID 34604222, 2021). "Through its regulation of BRCC3 expression, USP15 exerts control over the multiplication, invasiveness, and migration of bladder cancer cells." (PMID 38656882, 2024). "Our results indicate that high BRCC3 expression activates NF-κB signaling by targeting TRAF2 for activation, which in turn facilitates tumorigenesis in bladder cancer." (PMID 34604222, 2021). "BRCC3 exerts its oncogenic role via binding to TRAF2, which in turn leads the activation of NF-κB signaling in bladder cancer." (PMID 34604222, 2021). "To study the role of BRCC3 in the biological behaviors, we created wild type BRCC3 (BRCC3 WT) overexpression and BRCC3 deubiquitinating enzyme-null mutant (H122Q, BRCC3 HQ) overexpression UMUC3 bladder cancer cell lines via lentiviral transfection." (PMID 34604222, 2021). "To confirm this finding, we tested whether BRCC3 can activate the luciferase activity of an NF-κB reporter in both HEK293 cells and three bladder cancer cell lines 5637, T24, and EJ." (PMID 34604222, 2021). "BRCA1 is a crucial component of the BRCC3 complex, leading to our conjecture that USP15 may activate the NF-κB pathway by deubiquitinating BRCC3, thereby augmenting its expression and ultimately influencing bladder cancer progression." (PMID 38656882, 2024). "BRCC3 expression is up-regulated in bladder cancer patients which indicates a negative prognosis." (PMID 34604222, 2021).
breast tumors (4 papers, 2014 to 2019). "BRCC3 has been found to be aberrantly expressed in breast tumors and involved in DNA damage response." (PMID 26024915, 2015). "Moreover, the knockdown of BRCC3 (BRCC36) in cooperation with ionizing radiation can increase breast tumor cells undergoing apoptosis." (PMID 25337721, 2014). "Furthermore, BRCC3 is overexpressed in the vast majority of breast tumors." (PMID 26024915, 2015).